TOX (thymocyte selection associated high mobility group box)
Diseases named in the same sentence as TOX in open-access papers (continued):
Sharing a sentence is not in itself a finding about the gene and the disease.
Sepsis (1 paper, 2025). Sepsis is defined as life-threatening organ dysfunction caused by a dysregulated host response to infection. "This approach identified TOX as the “master switch” transcription factor driving exhaustion: its expression peaks at 36–48 h post-sepsis—8.4-fold above baseline (p< 0.001)—and then initiates a cascade of irreversible epigenetic and transcriptional changes." (PMID 40861459, 2025).
uveal melanoma (1 paper, 2020). A melanoma derived from melanocytes of the uveal tract. "UVM (uveal melanoma) also shows similar characteristic but the TOX expression change is unknown because of unsuitability to compare the different TOX expression between UVM and normal tissues." (PMID 32700817, 2020).
tumor (174 papers, 2012 to 2026). "As the immunosuppressive tumor microenvironment can induce T cell exhaustion, we assessed the transcription factor thymocyte selection-associated HMG BOX (TOX), which has been associated with exhausted T cells, in tumor-infiltrating CD8+ T cells." (PMID 40502703, 2025). "Mutations in SETD1B were also strongly associated with increased tumor infiltration with CD8+PD-1+TOX+ T cells, highlighting a potential link between this genetic alteration and immune recognition." (PMID 38653864, 2024). "Double-deficient CAR-tumor-infiltrating lymphocytes (TILs) of TOX and TOX2 showed increased cytokine expression and decreased inhibitory receptor expression, and more efficiently prevented tumor growth than wild-type CAR-T cells." (PMID 38918817, 2024). "By competing for intratumoral IL-2, Tregs prevented the activation of CD8+ tumor-infiltrating lymphocytes, drove thymocyte selection-associated high mobility group box protein (TOX) induction, and induced bona fide CD8+ T cell exhaustion." (PMID 38787791, 2024). "Molecular research suggests that transcription factors CREB1, AHR, and TOX drive tumor growth and metastasis and are associated with poor prognosis of DLBCL." (PMID 38099311, 2023). "TOX is overexpressed in tumor infiltrating cells and is associated with an increased expression of the inhibitory programmed-death protein." (PMID 35054387, 2022). "Here, we describe a new CRC tumor suppressor and potential therapeutic target: thymocyte selection associated high mobility group box (TOX) protein." (PMID 33897695, 2021). "As tumor mutation burden and tumor microenvironment play vital roles in the occurrence and development of tumors, we analyzed the TOX expression in the immune microenvironment of CRC." (PMID 33897695, 2021). "In our study, TOX was found to negatively associate with macrophages, suppressing the permissive tumor microenvironment of GBM." (PMID 32762688, 2020). "In general, T-cell exhaustion appeared to be more advanced in tumour-specific CD8+ T-cells from non-infected mice, as indicated by a higher proportion of the Thymocyte selection-associated high mobility group box protein (TOX)-expressing tumour-specific CD8+ T-cells compared to infected mice." (PMID 38271469, 2024). "Moreover, thymocyte selection-associated high mobility group box protein (TOX), which promotes exhaustion of tumor-infiltrating CD8+ T cells within the tumor, can be used to stratify patients during anti-tumor therapy, including anti-PD-1 immunotherapy." (PMID 37187731, 2023). "Moreover, those unique clusters expressed TOX, a marker of malignant lymphocytes, and a significant although heterogeneous over-expression of genes associated with tumour cell proliferation, tumorigenesis, and resistance to apoptosis." (PMID 32751918, 2020). "Despite this, it seems that TOX could play an important pathogenic role in the context of CTCL tumor formation by enhancing the survival of malignant T cells." (PMID 32106280, 2020). "Given that genomic alternations may promote the progression of tumor through transforming the tumor microenvironment, these results suggest that TOX expression is associated with benign biological processes." (PMID 32762688, 2020). "The underlying mechanism may be the indispensable role of TOX in the development of innate lymphoid cells and regulation of tumor‐specific T cells, which exerts an important effect on tumor microenvironment." (PMID 32700817, 2020). "In addition to being closely linked to the tumor microenvironment, TOX is also related to the tumor itself, which is the cause of tumor development and may therefore be a potential target of cancer therapies." (PMID 36969216, 2023). "One study reported that both TOX and TOX2-deficient CAR-T were able to suppress tumor growth and prolong survival of tumor-bearing mice." (PMID 41502492, 2026).
tumor (continued). "Loss of KLF2 led to increased TOX expression, impaired effector differentiation, and increased exhaustion program, with reduced antitumor capacity against B16-CD19 tumor." (PMID 40693464, 2025). "For example, BATF overexpression in TILs attenuates TOX locus opening and TOX expression, and CD4+ T cell help in CD8+ T cell–dendritic cell–CD4+ T cell triads within a tumor prevents TOX locus opening and ameliorates CD8+ T cell exhaustion." (PMID 40746547, 2025). "This study offers novel insights into the complex regulation of TOX by AHR, highlighting that AHR functions as a tumor suppressor by repressing TOX transcription." (PMID 40303305, 2025). "Our findings reveal that AHR suppresses CSC formation triggered by low-dose As3+ (0.5 μM) via transcriptional repression of TOX, a high mobility group box DNA binding protein that play a critical role in T cell exhaustion within tumor immunology." (PMID 40303305, 2025). "In contrast, there was a decreased density of activated CD4 T cells (CD45RA+GITR+TOX-) and CD8 T cells (CD45RA+GzmB+TOX-) in proximity to tumor cells." (PMID 39803458, 2025). "Protein analysis showed that the level of TCF1 in peri-tumor was significantly higher than that in tumor tissue, and TOX expression level in tumor tissue was higher than that in peri-tumor, which was consistent with transcriptome expression level." (PMID 40040705, 2025). "In contrast, non-converters’ tumors had a higher abundance of tumor cells and tumor cells expressing PD-L1, and more CD8 T cells expressing thymocyte selection-associated high mobility group box (TOX) protein, a marker of T cell exhaustion." (PMID 39190534, 2024). "Deletion of TOX in tumour-specific T cells reversed the exhaustion phenotypes with reduced inhibitory receptors and increased expression of TCF-1, but remained a dysfunctional and impaired effector function status." (PMID 38581063, 2024). "The fusion protein led to the expansion of CD8+ tumor infiltrating lymphocytes (TILs) with a less exhausted phenotype, expressing lower levels of PD-1 and TOX and higher levels of TCF-1." (PMID 39114660, 2024). "The TFs we evaluated (e.g., TCF1, T-BET, TOX) coordinate the interplay of these exhausted CD8+ T cell subsets, but their expression in tumor-associated T cells can vary in different microenvironments." (PMID 38775157, 2024). "Here, we observed two distinct TIM3 expression patterns (high & low) in T-ALL cell lines or tumor samples with high TOX and TOX2 levels based on a GEO public database analysis." (PMID 39080376, 2024). "When analyzing transcription factors that regulate T‐cell exhaustion among differentially expressed genes in the CD8+ TILs of human NSCLC and melanoma, TOX was observed as the only transcription factor expressed in both tumour types." (PMID 39169517, 2024). "UMAP plots of representative CD8+ T cells revealed a distinct subset of PD-1hi cells co-expressing TOX, Ki67, and CD39, which are associated with T-cell exhaustion, proliferative activity, and tumor specificity, respectively." (PMID 39426955, 2024). "Consistent with the CNV results, the expression of tumor-associated genes, including KIR3DL2, TOX, TWIST1, and GTSF1, upregulated along the CD4+ T-cell trajectory." (PMID 39963655, 2024). "We observed a similar result by flow cytometry, with anti-PD-L1 + anti-TIGIT treatment, but not anti-PD-L1 + anti-TIGIT + anti-CSF-1R treatment, driving a reduced expression of TOX in tumour CD8+ T cells." (PMID 38418879, 2024). "Our findings indicated that immune checkpoints (PDCD1, ENTPD1 and TIGIT), the T-cell exhaustion state-associated transcription factor TOX, and the gene DDX58 (transcriptional protein RIG-I) are co-expressed in tumour-infiltrating CD8+ T cells (Fig. EV1A–D)." (PMID 39322862, 2024).
tumor (continued). "Higher levels of TOX were observed as CD8+ T cells became more exhausted, indicating an association between the expression of TOX and the severity of tumour‐infiltrating T‐cell exhaustion." (PMID 39169517, 2024). "In human NSCLC and melanoma models, TOX was converged as vital TFs in mediating the exhaustion of TILs through upregulating immune checkpoints in tumour sites." (PMID 38581063, 2024). "We found that CAC exhibited a significantly enriched presence of TIGIT and TOX compared to corresponding tumor-free or even inflamed mucosa." (PMID 37835436, 2023). "Anti-vascular endothelial growth factor-A (VEGFA) antibody was reported to greatly limit tumor growth and reduce the levels of TOX and NFAT in mouse colon cancer models." (PMID 37398660, 2023). "Of note, CXCL13+ PD1+ TOX+ CD8 T cell population was recently reported to comprise a high fraction of tumor antigen-specific CD8 T cells." (PMID 37435085, 2023). "Kynurenine upregulate immune checkpoint expression and promote TEX in CRC via upregulating TOX expression, while IDO1 inhibitors and TOX knockdown can restore the anti-tumor activity of CD8+ T cells." (PMID 37180158, 2023). "In HCC, TOX promotes the exhaustion of tumor-antigen-specific CD8+ T cells by inhibiting PD-1 degradation and therefore increasing PD-1 expression on TILs." (PMID 37239368, 2023). "On the other hand, we found that positive TOX expression was present in PD-L1-positive immune cells homing both primary tumor and thrombus." (PMID 36042047, 2023). "We provide evidence that orthogonal combinatorial T-cell engineering reprograms tumor-specific TILs away from canonical TOX+ exhaustion, thereby overcoming homeostatic barriers to engraftment and leading to tumor regression." (PMID 37081150, 2023). "Early studies have reported that TOX is a tumor cell-specific marker of CTCLs including early MF based on immunohistochemical findings, as it is expressed in tumor cells of cutaneous T-cell lymphomas (CTCLs) but barely in inflammatory infiltrate of BIDs." (PMID 35642346, 2023). "The frequency of high nuclear TOX expression in both analyzed compartments was the same (n = 35, 48%), but many cases showed discrepant staining status in tumor mass and venous thrombus (p = 0.067, chi-square)." (PMID 36042047, 2023). "Previous research demonstrated that the expression of TOX is high in dysfunctional tumor-specific CD8+ T cells, which is driven by nuclear factor of activated T-cell (NFAT) activation and chronic TCR stimulation." (PMID 36776832, 2023). "Instead, the IR-coding genes and TOX, co-markers of tumor-reactive exhaustion were split across two distinct clusters, inflamed memory-like and tolerogenic c-Maf signaling." (PMID 37968259, 2023). "In tumor-specific TILs from mice and humans, TOX expression is positively correlated with the coexpression of inhibitory receptors and the low production of inflammatory cytokines." (PMID 36776832, 2023). "Multiple immunofluorescence staining showed that TOX was not only expressed in the tumor cells but also in CD8 + T cells." (PMID 36434543, 2022). "For example, CAR-T cells with Nrf4A family proteins knocked out had improved tumor-directed efficacy in mouse models, and knockout of TOX improved CAR-T cell efficacy as well." (PMID 36684449, 2022). "The results showed TOX was significantly highly expressed in tumor tissues compared with normal adjacent tissues." (PMID 36434543, 2022). "TOX is required for the development of various T-cell subsets and was described as putative tumor suppressor in MCD DLBCL30." (PMID 35538064, 2022). "Over the last few years several studies have evaluated the TOX expression in various neoplasms demonstrating that TOX is involved in the differentiation of “tumour-specific” T cells and in the “exhaustion” (anergy) of CD8+ T lymphocytes." (PMID 35885488, 2022).
tumor (continued). "Recent studies have also highlighted the important role of the TOX transcriptional regulator in driving T cell exhaustion and diminishing anti-tumor or anti-viral functions." (PMID 36084049, 2022). "The TOX was the critical regulator of the differentiation of tumor-specific T cells, which also showed a constant upregulation during this process." (PMID 36483553, 2022). "Recent studies have shown that TOX is a crucial transcription factor that contributes to T cell exhaustion and is involved in tumor development." (PMID 34692519, 2021). "Early studies reported TOX to be a tumor cell-specific marker of CTCLs including early MF based on immunohistochemical findings that TOX was expressed in tumor cells of CTCLs but hardly in inflammatory infiltrates of BIDs." (PMID 34574062, 2021). "Consistent with a role as a tumor-suppressor, TOX inhibited cancer cell proliferation and migration, likely by promoting the expression of epithelial markers and reducing mesenchymal markers, and promoted cancer cell apoptosis in vitro." (PMID 33897695, 2021). "TOX has been foremost studied in TCR-mediated exhaustion of mouse CD8+ T cells in the context of tumor or chronic infection." (PMID 34032638, 2021). "Quantitative real-time PCR (qRT-PCR) comparing 30 CRC and paired para-CRC tissues also presented significantly reduced TOX mRNA level in tumor samples (p < 0.0001)." (PMID 33897695, 2021). "TOX is a newly discovered gene, and three consecutive articles published in Nature refer to the role of the TOX gene in tumor immunotherapy." (PMID 34620162, 2021). "It is found that the expression of TOX was lower in CRC tumors (n = 275) than in non-tumor (n = 349) tissues." (PMID 33897695, 2021). "In this study, we showed that TOX appeared to act as a tumor suppressor in CRC: TOX expression was lower in CRC cells than para-CRC tissue." (PMID 33897695, 2021). "Other group reported that TOX was expressed by more than 50% of tumor cells in 83% of MF cases, whereas only 2% of inflammatory dermatoses cases showed TOX expression in more than 50% infiltrating lymphocytes." (PMID 34574062, 2021). "Overall, we observed a significant increase in IL-4 and TOX expression in the tumor stage, with a positive correlation between the levels of TOX and IL-4 expression." (PMID 34220814, 2021). "Downregulating TOX expression improves the anti-tumor function of CD8+ T cells, which can synergize with immune checkpoint suppression by anti-PD1, providing a promising strategy to enhance cancer immunotherapy." (PMID 33897695, 2021). "To explore the mechanism by which TOX inhibits tumor cell proliferation, migration, invasion, and EMT, we performed gene set enrichment analysis (GSEA) on TCGA data (n = 588)." (PMID 33897695, 2021). "Thymocyte selection-associated high mobility group box protein (TOX) and P-selectin glycoprotein ligand-1 (PSGL-1) modulate the tumor microenvironment by depleting CD8 + T cells, and they hold promise as targets for tumor immunotherapy." (PMID 34045512, 2021). "Taken together, these findings highlight the tumor-suppressive role of TOX in CRC, especially in MSI CRC, and provide valuable information that rapamycin alone or combined with PD1 inhibitor has therapeutic potential in CRC." (PMID 33897695, 2021). "With the increase of tumor stage, TOX expression decreased, indicating the presence of TOX relates to better overall survival (OS)." (PMID 33897695, 2021). "Immunohistochemical semi-quantitative analysis showed that primary CRC tissues (2.15 ± 1.688) had significantly lower levels of TOX protein staining (p = 0.004) than adjacent non-tumor tissues (4.45 ± 2.050)." (PMID 33897695, 2021). "As a result, downregulation of TOX proteins can lead to an improvement in the anti-tumor function of CD8 T cells." (PMID 34696292, 2021).